ENSG00000261130 (novel protein)
Gene: Protein-coding gene on chromosome 16 (15,395,754 to 15,515,348, forward strand). Ensembl gene ENSG00000261130.
Genetic constraint (gnomAD): Loss-of-function variants: 12 observed, 7.48 expected, observed/expected ratio (o/e) 1.6, 90% interval 0.98 to 1.94. That is too few expected variants to judge how well the gene tolerates losing a copy. Missense variants: 187 observed, 119.92 expected, observed/expected ratio (o/e) 1.56, 90% interval 1.38 to 1.76. Synonymous variants: 81 observed, 48.25 expected, observed/expected ratio (o/e) 1.68, 90% interval 1.4 to 1.93.